TARDBP (TAR DNA binding protein)
Diseases named in the same sentence as TARDBP in open-access papers (continued):
Sharing a sentence is not in itself a finding about the gene and the disease.
amyotrophic lateral sclerosis (continued). "Many neurodegenerative diseases, including Alzheimer's, Parkinson's, amyotrophic lateral sclerosis (ALS), are caused by the misfolding and aggregation of proteins such as tau, alpha‐synuclein, superoxide dismutase 1 (SOD1), and TAR DNA‐binding protein‐43 (TDP‐43; Lansbury & Lashuel, 2006)." (PMID 30143514, 2018). "Pathological TAR DNA-binding protein 43 (TDP-43) is a major component of inclusions that are found in most cases of amyotrophic lateral sclerosis (ALS) and in frontotemporal lobar degeneration (FTLD)." (PMID 30061532, 2018). "TAR DNA binding protein 43 (TDP-43) is the main disease protein in most patients with amyotrophic lateral sclerosis (ALS) and about 50% of patients with frontotemporal dementia (FTD)." (PMID 30326935, 2018). "In 2006, TAR DNA-binding protein-43 (TDP-43) was identified as the major constituent of ubiquitin-positive inclusions in patients with Amyotrophic Lateral Sclerosis (ALS) and Frontotemporal Lobar Degeneration (FTLD)." (PMID 30541625, 2018). "Tar DNA binding protein 43 (TDP-43) is the principal component of ubiquitinated protein inclusions present in nervous tissue of most cases of both amyotrophic lateral sclerosis (ALS) and frontotemporal dementia (FTD)." (PMID 29079747, 2017). "Recently, Tar DNA-binding protein-43 (TDP-43) and Fused in Sarcoma (FUS), two proteins intimately linked to fronto-temporal dementia and related amyotrophic lateral sclerosis (FTD/ALS) have also been shown to disrupt ER–mitochondria associations." (PMID 28337542, 2017). "Frontotemporal Dementia (FTD) and amyotrophic lateral sclerosis (ALS) are two neurodegenerative diseases associated to mislocalization and aggregation of TAR DNA-binding protein 43 (TDP-43)." (PMID 28066234, 2016). "Deposition of TDP-43 has been also been detected in some patients with amyotrophic lateral sclerosis (ALS), in consonance with the fact that these two diseases share some clinical and genetic features such as mutations the in TARDBP, FUS and C9orf72 genes." (PMID 27138926, 2016). "Frontotemporal lobar degeneration (FTLD) and amyotrophic lateral sclerosis (ALS) are types of major TDP-43 (43-kDa TAR DNA-binding protein) proteinopathy." (PMID 27338935, 2016). "More recently, highly ubiquitylated cytoplasmic inclusions of the TAR DNA-binding protein of 43 kDa (TDP-43) have been identified in neurons of Amyotrophic Lateral Sclerosis (ALS) affected patients." (PMID 28357271, 2015). "TAR DNA-binding protein 43 (TDP-43) is a nuclear protein, but it is redistributed in the neuronal cytoplasm in both amyotrophic lateral sclerosis (ALS) and frontotemporal lobar degeneration (FTLD)." (PMID 26334913, 2015). "Intraneuronal inclusions of TAR DNA-binding protein 43 (TDP-43) have been found in the majority of Amyotrophic Lateral Sclerosis (ALS) patients." (PMID 24938805, 2014). "Transactive response DNA-binding protein (TARDBP/TDP-43) is an RNA-processing protein that is involved in the pathogenesis of major neurodegenerative diseases, including amyotrophic lateral sclerosis (ALS) and frontotemporal dementia (FTD)." (PMID 25329970, 2014). "Mutations in TARDBP, encoding Tar DNA binding protein-43 (TDP43), cause amyotrophic lateral sclerosis (ALS) and frontotemporal dementia (FTD)." (PMID 24465814, 2014). "For example, mutations in TAR DNA binding protein (TARDBP; OMIM*605078) and FUS cause familial amyotrophic lateral sclerosis (ALS)." (PMID 25375143, 2014). "Abnormal processing of TAR DNA binding protein 43 (TDP-43) has been identified as a major factor in neuronal degeneration during amyotrophic lateral sclerosis (ALS) or frontotemporal lobar degeneration (FTLD)." (PMID 23840699, 2013). "Two proteins mutated in familial cases of amyotrophic lateral sclerosis (ALS) or FTLD, the RNA-binding proteins TAR DNA-binding protein-43 (TDP-43) and fused in sarcoma (FUS), have been identified in Microprocessor complexes." (PMID 23115562, 2012).
amyotrophic lateral sclerosis (continued). "Anterograde and retrograde trafficking is altered in Amyotrophic lateral sclerosis (ALS) mouse models in which SOD1, guanin-nucleotide exchange factor (GEF) and TAR DNA-binding protein 43 (TDP-43) are mutated." (PMID 22792111, 2012). "Recent advances in proteomics have allowed the identification of a new marker protein, TAR DNA-binding protein 43 kDa (TDP-43), for amyotrophic lateral sclerosis (ALS) and frontotemporal lobar degeneration (FTLD)." (PMID 23300771, 2012). "Mislocalization, aberrant processing and aggregation of TAR DNA-binding protein 43 (TDP-43) is found in the neurons affected by two related diseases, amyotrophic lateral sclerosis (ALS) and frontotemporal lobe dementia (FTLD)." (PMID 20967127, 2010). "Amyotrophic lateral sclerosis (ALS) is a fatal neurodegenerative disorder, most sporadic cases exhibiting TAR DNA-binding protein 43 (TDP-43) pathology." (PMID 42141160, 2026). "Notable examples are HD, caused by an expansion in the huntingtin gene (HTT), and certain familial forms of amyotrophic lateral sclerosis (ALS) that are considered monogenic, associated with mutations in SOD1 (superoxide dismutase), TARDBP (Transactive response DNA-binding protein), or FUS." (PMID 39857412, 2025). "Co-occurrence of double heterozygosity in TARDBP and C9ORF72 is exceedingly rare in amyotrophic lateral sclerosis." (PMID 40981770, 2025). "Amyotrophic lateral sclerosis (ALS) is an incurable neurodegenerative disease characterized by the cytoplasmic mislocalization and accumulation of TAR DNA binding protein 43 (TDP-43)." (PMID 40940222, 2025). "Furthermore, connections with FUS, TARDBP, and NEFL, all linked to amyotrophic lateral sclerosis (ALS), highlight SOD1’s involvement in neurodegenerative disease pathways." (PMID 40710578, 2025). "Mutations in the TARDBP gene encoding TDP-43 protein are linked to loss of function in neurons and familial frontotemporal dementia (FTD) and amyotrophic lateral sclerosis (ALS)." (PMID 40238886, 2025). "Two proteins, namely fused in sarcoma (FUS) and TAR DNA binding protein-43 (TDP-43), are known to induce hyperactivation of GSK-3β and lead to amyotrophic lateral sclerosis (ALS)." (PMID 40148800, 2025). "The neurodegenerative disorders amyotrophic lateral sclerosis (ALS) and frontotemporal dementia (FTD) are united by the pathological mis-localization and aggregation of TAR DNA-binding protein 43 (TDP-43) in affected neurons and glial cells." (PMID 41292965, 2025). "Amyotrophic lateral sclerosis (ALS) involves progressive degeneration of motor neurons, often associated with aggregated proteins such as superoxide dismutase 1 (SOD1) and TAR DNA-binding protein 43 (TDP-43)." (PMID 40940752, 2025). "These aggregates stem from reversible dynamic LLPS transitioning into irreversible clusters, such as α‐synuclein in Parkinson's disease (PD), tau in Alzheimer's disease (AD), fused in sarcoma (FUS), and TAR DNA‐binding protein 43 (TDP‐43) in amyotrophic lateral sclerosis (ALS)." (PMID 41268324, 2025). "The TARDBP gene, which encodes the transactive response DNA‐binding protein of 43 kDa (TDP‐43), is recognized as crucial in the pathogenesis of frontotemporal dementia (FTD), amyotrophic lateral sclerosis (ALS) and motor neuron disease." (PMID 39031474, 2024). "Amyotrophic Lateral Sclerosis (ALS) and FTD show formation of cytoplasmic TAR DNA-binding protein (TDP-43) aggregates." (PMID 38685916, 2024). "Frontotemporal lobar degeneration with ubiquitin-positive inclusions (FTLD-TDP), amyotrophic lateral sclerosis (ALS) and limbic-predominant age-related TDP-43 encephalopathy (LATE) are associated with deposition of cytoplasmic inclusions of TAR DNA-binding protein 43 (TDP-43) in neurons." (PMID 38997630, 2024). "For Amyotrophic Lateral Sclerosis (ALS), an aptamer has been identified for targeting TAR-DNA-Binding Protein 43 (TDP-43)." (PMID 38474636, 2024).
amyotrophic lateral sclerosis (continued). "As an example, the cytoplasmic and mitochondrial accumulation of TAR DNA-binding protein 43 (TDP-43, whose mutations are associated with amyotrophic lateral sclerosis (ALS) and frontotemporal dementia (FTD)) determines the release of mtDNA (one of the best-characterized mtDAMPs) in the cytoplasm." (PMID 37973903, 2023). "In amyotrophic lateral sclerosis (ALS), several polypeptides are inclined to misfold and aggregate, such as Tar DNA binding protein-43 (TDP-43), superoxide dismutase 1 (SOD1) and ubiquilin-2." (PMID 37107340, 2023). "For instance, exosomal superoxide dismutase 1 (SOD1), exosomal dipeptide-repeat proteins (DPRs), exosomal TAR DNA-binding protein (TARDBP), and fused in sarcoma (FUS) have all been found to affect the spread of amyotrophic lateral sclerosis." (PMID 36834471, 2023). "TAR DNA-binding protein 43 (TDP-43) inclusion pathology, which is characteristic of frontotemporal lobar degeneration and amyotrophic lateral sclerosis, is also commonly found." (PMID 36100231, 2023). "TAR DNA-binding protein 43 (TDP-43), an RNA binding factor, forms pathologic aggregates in all genetic and sporadic forms of amyotrophic lateral sclerosis, and is a consistent pathologic feature in frontotemporal dementia (FTD) and progressive muscle atrophy." (PMID 37545643, 2023). "In Amyotrophic lateral sclerosis (ALS), the main pathological protein found aggregated in the cytoplasm of neurons leading to progressive degeneration of motor neurons is TAR DNA-binding protein 43 (TDP-43)." (PMID 35434769, 2022). "Likewise, TARDBP aggregates are a common feature in both amyotrophic lateral sclerosis (ALS) and frontotemporal lobar degeneration (FTLD) pathology despite their genetic heterogeneity." (PMID 36136249, 2022). "This disturbed nuclear–neuritic translocation of aSyn resembles the mislocalization of TAR DNA-binding protein 43 (TDP-43) from the nucleus to cytoplasm described in frontotemporal dementia (FTD) and amyotrophic lateral sclerosis." (PMID 36009004, 2022). "In mice with amyotrophic lateral sclerosis (ALS), accumulated TAR DNA-binding protein 43 in the cytoplasm can lead to mtDNA leakage and thus activate cGAS, ultimately causing upregulation of NF-κB and IFN-1 levels." (PMID 36545321, 2022). "In primary neurons of Amyotrophic Lateral Sclerosis (ALS) disease models, intronic circRNAs concentrate in cytoplasm decoying TAR DNA-Binding protein 43 (TDP-43) and avoiding the accumulation of toxic TDP-43 aggregates." (PMID 35456950, 2022). "Similarly, TAR DNA-binding protein 43 (TDP-43), which promotes amyotrophic lateral sclerosis (ALS) and frontotemporal lobar degeneration (FTLD), interacts with stalled ribosomes during cellular stress and inhibits protein synthesis." (PMID 33674575, 2021). "In amyotrophic lateral sclerosis (ALS), TAR DNA binding protein 43 (TDP-43) aggregation occurs in the brain; drugs that target this protein have become a therapeutic approach to this disease." (PMID 34685709, 2021). "A landmark discovery in 2006 identified TAR DNA-binding protein 43 (TDP-43) accumulation as a pathological hallmark of both amyotrophic lateral sclerosis (ALS) and frontotemporal dementia (FTD), thus linking the disease mechanisms of ALS and FTD1,2." (PMID 32184412, 2020). "Since its discovery as a primary component in cytoplasmic aggregates in post-mortem tissue of patients with Amyotrophic Lateral Sclerosis (ALS), TAR DNA Binding Protein 43 kDa (TDP-43) has remained a central focus to understand the disease." (PMID 32799899, 2020). "C-terminal fragments of Tar DNA-binding protein 43 (TDP-43) have been identified as the major pathological protein in several neurodegenerative diseases, including amyotrophic lateral sclerosis (ALS) and frontotemporal dementia (FTD)." (PMID 33154354, 2020).
amyotrophic lateral sclerosis (continued). "TAR DNA-binding protein 43 (TDP-43) is the major component of the ubiquitin-positive protein aggregates seen in the majority of frontotemporal lobar degeneration and amyotrophic lateral sclerosis cases." (PMID 31213972, 2019). "The neuromuscular disorder amyotrophic lateral sclerosis (ALS) is characterized by protein inclusions formed by either TAR DNA-binding protein of 43 kDa (TDP-43), Cu/Zn superoxide dismutase (SOD1), or fused in sarcoma (FUS), in both upper and lower motor neurons." (PMID 31736708, 2019). "Several genes have been linked to the onset of amyotrophic lateral sclerosis (ALS, OMIM # 105400), including SOD1, C9ORF72, TARDBP, and FUS, though roughly 80% of cases are of unknown etiology." (PMID 29776328, 2018). "Aggregation of TAR DNA-binding protein of 43 kDa (TDP-43) is implicated in the pathogenesis of sporadic and certain familial forms of amyotrophic lateral sclerosis (ALS), suggesting elimination of TDP-43 aggregates as a possible therapeutic strategy." (PMID 29662239, 2018). "TAR-DNA-binding protein-43 (TDP-43) C-terminus encodes a prion-like domain widely presented in RNA-binding proteins, which functions to form dynamic oligomers and also, amazingly, hosts most amyotrophic lateral sclerosis (ALS)-causing mutations." (PMID 26735904, 2016). "Tar DNA binding protein 43 (TDP-43) hyperphosphorylation, caused by Casein kinase 1 (CK-1) protein isoforms, is associated with the onset and progression of Amyotrophic Lateral Sclerosis (ALS)." (PMID 28155653, 2016). "TAR DNA-binding protein 43 (TDP-43) inclusions are pathological hallmarks of patients with frontotemporal lobar degeneration (FTLD) and amyotrophic lateral sclerosis (ALS)." (PMID 26555887, 2015). "TAR DNA-binding protein (TDP-43, also known as TARDBP) is the major pathological protein in amyotrophic lateral sclerosis (ALS) and frontotemporal dementia (FTD)." (PMID 24424030, 2014). "The majority of cases of frontotemporal lobar degeneration and amyotrophic lateral sclerosis are pathologically defined by the cleavage, cytoplasmic redistribution and aggregation of TAR DNA binding protein of 43 kDa (TDP-43)." (PMID 24466128, 2014). "The TDP-43 proteinopathies are a group of diseases with overlapping clinicopathological features including amyotrophic lateral sclerosis (ALS) and frontotemporal lobar degeneration with TAR DNA-binding protein (TDP-43) inclusions (FTLD-TDP)." (PMID 24651281, 2014). "Ubiquitinated TAR DNA-binding protein–43 (TDP-43) is a major disease protein in FTLD and amyotrophic lateral sclerosis (ALS) and can occasionally be observed in Lewy body disorders and tauopathies." (PMID 23664753, 2013). "Tar DNA-binding protein 43 (TDP-43) is the principal component of ubiquitinated inclusions in frontotemporal lobar degeneration with TDP-43-positive inclusions (FTLD-TDP) and amyotrophic lateral sclerosis (ALS)." (PMID 23922830, 2013). "The 43 kDa TAR DNA-binding protein (TDP-43) and its C-terminal proteolytic fragments have been identified as the major component of inclusion bodies in amyotrophic lateral sclerosis (ALS) and frontotemporal lobar degeneration with unbiquitin-positive inclusions (FTLD-U)." (PMID 23737961, 2013). "In amyotrophic lateral sclerosis (ALS) and frontotemporal lobar degeneration, TAR DNA binding protein 43 (TDP-43) accumulates in the cytoplasm of affected neurons and glia, where it associates with stress granules (SGs) and forms large inclusions." (PMID 24312274, 2013). "MS: multiple sclerosis; ALS: amyotrophic lateral sclerosis; TDP-43: TAR DNA-binding protein 43; IL: interleukin; IGF: insulin growth factor; SOD: superoxide dismutase; NO: nitric oxide; TNF: tumour necrosis factor." (PMID 22269588, 2012). "Amyotrophic lateral sclerosis (ALS) and frontotemporal lobar degeneration (FTLD) are characterized by intraneuronal deposition of the nuclear TAR DNA-binding protein 43 (TDP-43) caused by unknown mechanisms." (PMID 21829535, 2011).
amyotrophic lateral sclerosis (continued). "Tar DNA Binding Protein-43 (TDP-43) is a principle component of inclusions in many cases of frontotemporal lobar degeneration (FTLD-U) and amyotrophic lateral sclerosis (ALS)." (PMID 20948999, 2010). "Inclusions of TAR DNA binding protein-43 (TDP-43) are the defining histopathological feature of frontotemporal lobar degeneration with ubiquitin-positive inclusions (FTLD-U) and amyotrophic lateral sclerosis (ALS)." (PMID 20804554, 2010). "Recently, the TAR DNA-binding protein 43 (TDP-43) was identified as the disease accumulating protein in patients with frontotemporal lobar degeneration with ubiquitin inclusions (FTLD-U) and in amyotrophic lateral sclerosis (ALS)." (PMID 18802454, 2008). "TAR DNA binding protein, encoded by TARDBP, was shown to be a central component of ubiquitin-positive, tau-negative inclusions in frontotemporal lobar degeneration (FTLD-U) and amyotrophic lateral sclerosis (ALS)." (PMID 18545701, 2008). "Redistribution of nuclear TAR DNA binding protein 43 (TDP-43) to the cytoplasm and ubiquitinated inclusions of spinal motor neurons and glial cells is characteristic of amyotrophic lateral sclerosis (ALS) pathology." (PMID 18957104, 2008). "The TAR DNA-binding protein 43 (TDP-43) has been identified as the major disease protein in amyotrophic lateral sclerosis (ALS) and frontotemporal lobar degeneration with ubiquitin inclusions (FTLD-U), defining a novel class of neurodegenerative conditions: the TDP-43 proteinopathies." (PMID 18802454, 2008). "Pathological inclusions of the C-terminal domain (CTD) of TAR DNA binding protein-43 (TDP-43) are neurodegenerative hallmarks in amyotrophic lateral sclerosis (ALS) and frontotemporal dementia, yet CTD’s aggregation propensity complicates structural characterization of native TDP-43." (PMID 41298366, 2025). "TAR DNA-binding protein 43 (TDP-43), a protein involved in RNA processing, becomes mislocalized in diseases such as amyotrophic lateral sclerosis (ALS) and FTD, forming cytoplasmic aggregates that disrupt RNA metabolism and lead to neuronal dysfunction and death." (PMID 40558545, 2025). "In amyotrophic lateral sclerosis (ALS), TAR DNA-binding protein 43 (TDP-43) is involved." (PMID 40141135, 2025). "The expression of ATG7 was decreased in brain tissues from amyotrophic lateral sclerosis (ALS)-frontotemporal dementia (FTD) patients, and upregulation of ATG7 could alleviate motor neuron dysfunction associated with deficiency of TARDBP/TDP-43 (TAR DNA binding protein)." (PMID 38227600, 2024). "Furthermore, in patients with amyotrophic lateral sclerosis (ALS), neurofilaments (NFs) and TAR DNA binding protein 43 (TDP-43) tend to accumulate in the cytoplasm." (PMID 37168679, 2023). "In amyotrophic lateral sclerosis (ALS), according to postmortem studies, four neuropathological stages of disease progression can be defined based on the regional distribution of the phosphorylated 43 kDa TAR DNA-binding protein (pTDP-43) in the brain." (PMID 36763176, 2023). "Amyotrophic Lateral Sclerosis (ALS) is characterised by a loss of motor neurons in the brain and spinal cord that is preceded by early-stage changes in synapses that may be associated with TAR-DNA-Binding Protein 43 (TDP-43) pathology." (PMID 37671010, 2023). "The major aggregating protein in amyotrophic lateral sclerosis and frontotemporal dementia, the RNA‐binding protein TAR DNA‐binding protein (TDP‐43), is hyperphosphorylated in disease on several C‐terminal serine residues, a process generally believed to promote TDP‐43 aggregation." (PMID 35112738, 2022). "Mutations in the RBPs, TAR DNA (TARDBP), FUS RNA-binding protein (FUS), Ataxin 2 (ATXN2) as well as EWS RNA-binding proteins (EWSR1) and many more have been shown to greatly influence disease risks, e.g., amyotrophic lateral sclerosis (ALS) and frontotemporal dementia (FDT)." (PMID 35202165, 2022).